DMD (dystrophin)
Diseases named in the same sentence as DMD in open-access papers (continued):
Sharing a sentence is not in itself a finding about the gene and the disease.
Duchenne muscular dystrophy (continued). "Mutations in the DMD gene underlie a severe muscular dystrophy, Duchenne muscular dystrophy and a milder muscular dystrophy, Becker muscular dystrophy, depending on whether mutations disrupt or maintain the open reading frame, respectively." (PMID 26670121, 2016). "We also review recent data supporting therapeutic effects of resveratrol in the Duchenne Muscular Dystrophy, a fatal genetic disease affecting the production of muscle dystrophin, associated to a variety of mitochondrial dysfunctions, which likely contribute to disease pathogenesis." (PMID 27136581, 2016). "Indeed, hlh-1(cc561) exacerbated the effect of a dystrophin mutation associated with Duchenne’s muscular dystrophy, leading to muscle degeneration in adulthood." (PMID 28036392, 2016). "Furthermore, pharmacological enhancement of utrophin expression, a gene exclusively expressed in fetus but that can compensate Dystrophin loss of function in Duchenne Muscular Dystrophy is currently under investigation." (PMID 27805016, 2016). "Duchenne muscular dystrophy (DMD) is caused by mutations in the dystrophin gene." (PMID 26664665, 2015). "Dystrophin Dp40 is the shortest protein encoded by the DMD (Duchenne muscular dystrophy) gene." (PMID 26217814, 2015). "Locus-specific or gene-specific probes can be used to identify known aberrations that cause fetal or congenital abnormalities; for example, 22q11 deletions in DiGeorge syndrome, 7q11.23 deletions in Williams syndrome, and dystrophin mutations in Duchenne muscular dystrophy." (PMID 26237476, 2014). "Here we address this question by investigating whether fetal skeletal muscle progenitors (FMPs) isolated from Pax3GFP/+ embryos have the capacity to regenerate muscle after engraftment into Dystrophin-deficient mice, a model of Duchenne muscular dystrophy." (PMID 23671652, 2013). "However, it is important to note that Duchenne muscular dystrophy is caused by mutations in dystrophin, a main component of the dystroglycan complex that confers stability to the sarcolemma." (PMID 24052812, 2013). "Mutations in the DMD gene lead to muscle wasting, and two main phenotypes have been defined according to Monaco’s reading-frame theory: the severe Duchenne Muscular Dystrophy, due to out-of-frame mutations, and the milder Becker Muscular Dystrophy, associated with in-frame mutations." (PMID 23028937, 2012). "Duchenne muscular dystrophy (DMD) arises as a consequence of mutations in the dystrophin gene." (PMID 23209572, 2012). "Duchenne muscular dystrophy is caused by a mutation in the gene coding for the dystrophin protein." (PMID 22866241, 2012). "In Duchenne muscular dystrophy, mutations in the dystrophin gene lead to a deficiency of this protein in muscle sarcolemma, a component of the dystrophin-glycoprotein complex which forms an important link between the cytoskeleton and the extracellular matrix in the muscle." (PMID 22629149, 2012). "Finally, the resistance of mouse muscles to degeneration is seen in other mutations, such as dystrophin, mutations, which cause severe Duchenne muscular dystrophy in people, but a comparatively mild phenotype in the mdx/mdx mouse." (PMID 22242131, 2011). "Duchenne muscular dystrophy (DMD) is a progressive, X-linked, degenerative muscle disorder caused in the majority of cases by large out-of-frame deletions or duplication in the DMD gene that provoke the absence or dysfunction of the cytoskeletal protein dystrophin." (PMID 21886794, 2011). "As another example, MPprimer is able to design the multiplex PCR primers for DMD (dystrophin gene which caused Duchenne Muscular Dystrophy), which has 79 exons, for 20×, 20×, 20×, 14×, and 5× plex PCR reactions in five tubes to detect underlying exon deletions." (PMID 20298595, 2010).
Duchenne muscular dystrophy (continued). "The potential relevance of inducing muscle hypertrophy to the treatment of muscle disorders in humans has been suggested by studies involving mdx mice, which carry a mutation in the dystrophin gene and therefore serve as a genetic model of Duchenne's muscular dystrophy." (PMID 18795097, 2008). "Duchenne muscular dystrophy (DMD) is a severe X-linked neuromuscular disorder caused by loss-of-function mutations in the dystrophin gene, leading to progressive muscle degeneration, motor decline, respiratory compromise, and cardiomyopathy." (PMID 41892993, 2026). "Duchenne muscular dystrophy (DMD) is the most common muscular dystrophy, resulting from loss‐of‐function variants in the dystrophin gene." (PMID 41582627, 2026). "Pathogenic variants in the dystrophin (DMD) gene cause muscle-wasting disorders ranging from the milder Becker muscular dystrophy (BMD) to the more severe Duchenne muscular dystrophy (DMD)." (PMID 41502415, 2026). "Duchenne muscular dystrophy (DMD) is an X-linked disease caused by mutations in the dystrophin gene." (PMID 41965347, 2026). "Duchenne muscular dystrophy (DMD) is a fatal X-linked neuromuscular disorder caused by mutations in the dystrophin gene." (PMID 42121843, 2026). "Becker muscular dystrophy (BMD) and Duchenne muscular dystrophy (DMD) are X-linked recessive muscular dystrophies caused by pathogenic dystrophin (DMD) variants." (PMID 41262524, 2026). "Duchenne muscular dystrophy (DMD) and Becker muscular dystrophy (BMD) are genetic muscle disorders causing muscle fiber degeneration caused by mutations in the dystrophin (DMD) gene." (PMID 40904616, 2025). "Duchenne muscular dystrophy (DMD) is a progressive X-linked recessive disorder caused by mutations in the dystrophin gene, affecting approximately one in 3,500-5,000 live male births worldwide." (PMID 41393644, 2025). "Duchenne muscular dystrophy (DMD) is an X-linked recessive muscular dystrophy caused by pathogenic variants in the dystrophin gene (DMD), affecting patients from early childhood." (PMID 40649811, 2025). "In particular, mutations in dystrophin, one such protein, result in Duchenne muscular dystrophy (DMD), the most common form of muscular dystrophy." (PMID 40565081, 2025). "One of the well-known inherited diseases in this group is Duchenne muscular dystrophy (DMD), an inherited progressive disease associated with loss of the gene encoding dystrophin (DMD) lying on the X chromosome." (PMID 40650152, 2025). "Background and aims: Duchenne muscular dystrophy (DMD) is a severe X‐linked disorder caused by mutations in the DMD gene, leading to dystrophin deficiency and progressive muscle degeneration." (PMID 40542581, 2025). "For instance, dystrophin mutations (point mutations, small insertions/deletions, and large deletions or duplications) cause Duchenne muscular dystrophy (DMD) and an X-linked muscle wasting disease." (PMID 40558986, 2025). "Duchenne muscular dystrophy (DMD) arises from dystrophin deficiency, a crucial component of the dystrophin-glycoprotein complex (DGC) essential for maintaining cellular structural integrity by linking intracellular actin filaments to the basal lamina." (PMID 41467913, 2025). "Functional inactivation of the dystrophin gene is the primary cause of Duchenne muscular dystrophy (DMD) in humans and mdx mice, a mouse model of DMD." (PMID 40870015, 2025). "Duchenne muscular dystrophy (DMD) is a fatal X‐linked recessive disease caused by loss of dystrophin expression." (PMID 40641092, 2025). "Duchenne muscular dystrophy (DMD) is a severe X-linked disorder characterized by progressive muscle degeneration due to mutations in the dystrophin gene." (PMID 40724990, 2025). "Duchenne muscular dystrophy (DMD) is a fatal genetic muscle-wasting disease characterized by loss of dystrophin protein." (PMID 41307959, 2025).
Duchenne muscular dystrophy (continued). "Duchenne muscular dystrophy (DMD) is a rare, progressive and debilitating neuromuscular disease resulting from pathogenic variants in the DMD gene that lead to reduced levels of functional dystrophin." (PMID 41104521, 2025). "Duchenne muscular dystrophy (DMD), a rare X‐linked genetic disorder, is affecting skeletal and cardiac muscles due to the loss of the dystrophin protein." (PMID 41163301, 2025). "Duchenne muscular dystrophy (DMD) is a rare disease caused by mutations in the DMD gene that encodes dystrophin, an essential protein for maintaining muscle fiber integrity and stability." (PMID 40065476, 2025). "Duchenne muscular dystrophy (DMD) is a recessive X-linked severe neuromuscular disorder caused by mutations in the dystrophin gene that affects 1:5000 male births." (PMID 40048444, 2025). "Duchenne muscular dystrophy (DMD) is a progressive muscle-wasting disease caused by out-of-frame mutations in the DMD gene, resulting in dystrophin protein deficiency." (PMID 40483693, 2025). "The majority of the BMD biomarker studies employ targeted approaches and focus on translating findings from Duchenne Muscular Dystrophy (DMD), a more severe disease form with clinical similarities but caused by out-of-frame mutations in the dystrophin gene." (PMID 40483507, 2025). "Among these, duchenne muscular dystrophy (DMD) is the most prevalent type, arising from mutations in the DMD gene, with an X-linked recessive inheritance pattern." (PMID 41267743, 2025). "Absence of dystrophin protein causes cardiac dysfunction in patients with Duchenne muscular dystrophy (DMD)." (PMID 40634289, 2025). "Duchenne muscular dystrophy (DMD) is a severe and progressive form caused by the loss of function of the dystrophin gene (DMD) on the X chromosome." (PMID 40695994, 2025). "Duchenne muscular dystrophy (DMD) is a severe, X-linked disease caused by mutations in the dystrophin gene resulting in progressive skeletal and cardiac muscle degeneration." (PMID 41301745, 2025). "Mutations, particularly single-point amino acid substitutions, can lead to dysfunctional Dystrophin, causing muscular dystrophies, with Duchenne muscular dystrophy (DMD) being the most severe form." (PMID 39981262, 2025). "Duchenne muscular dystrophy (DMD) is a genetic disorder characterized by progressive muscle degeneration and weakness caused by mutations in the dystrophin gene, resulting in skeletal and cardiac muscle damage." (PMID 40859366, 2025). "Duchenne muscular dystrophy (DMD) is a severe recessive X-linked muscle disease caused by mutations in the DMD gene, resulting in the absence in skeletal muscle of dystrophin, a protein essential to ensure structural integrity to muscle fibers." (PMID 40035839, 2025). "Duchenne muscular dystrophy (DMD), another X-linked disease, affects 1:3500 boys due to mutations in dystrophin (DMD) – a cytoskeletal protein required for myocyte membrane integrity." (PMID 40905915, 2025). "In Duchenne muscular dystrophy (DMD), mutations in the dystrophin gene not only affect skeletal muscle but also impact cardiac muscle, leading to cardiac dilation and eventual failure, progressing to DCM." (PMID 40166597, 2025). "For instance, a novel mutation in the dystrophin gene causing a disorder similar to human Duchenne muscular dystrophy (DMD) has been identified in a line of Australian labradoodles." (PMID 39935775, 2025). "Duchenne muscular dystrophy (DMD) is a progressive, X-linked inherited disease caused by mutations in the dystrophin gene." (PMID 40722287, 2025). "Both male and female monkeys showed dystrophin deficiency and muscle degeneration, like early Duchenne muscular dystrophy (DMD)." (PMID 40699729, 2025). "Duchenne muscular dystrophy (DMD) is a severe neuromuscular disorder primarily caused by mutations in the dystrophin gene, leading to progressive muscle degeneration." (PMID 40663516, 2025).
Duchenne muscular dystrophy (continued). "Duchenne Muscular Dystrophy (DMD) is an X-linked recessive neuromuscular disorder primarily affecting males, caused by mutations in the dystrophin gene." (PMID 39080230, 2025). "Duchenne muscular dystrophy (DMD) is an X-linked disorder that is caused by mutations in the DMD gene, leading to progressive muscle wasting and weakness." (PMID 39999085, 2025). "Duchenne muscular dystrophy (DMD) is an X-linked muscular dystrophy due to null mutations in the DMD gene that predominantly affects males, while heterozygous females are usually asymptomatic carriers." (PMID 40035839, 2025). "In Duchenne Muscular Dystrophy (DMD), for example, MuSCs suffer from an intrinsic polarity defect caused by the loss of dystrophin expression." (PMID 41309582, 2025). "Increasing evidence supports the contributing role of satellite cells in Duchenne muscular dystrophy (DMD), a lethal degenerative muscle disease caused by loss of dystrophin." (PMID 40473604, 2025). "Duchenne muscular dystrophy (DMD), the most common childhood muscular dystrophy, is a lethal, X‐linked neuromuscular disorder caused by complete deficiency of the protein dystrophin due to loss‐of‐function mutations in the DMD gene." (PMID 40830818, 2025). "The analysis of various muscles from mdx mouse, which is an animal model of the Duchenne muscular dystrophy (DMD), showed significant changes in mitochondrial function, associated with dystrophin deficiency." (PMID 41006931, 2025). "Duchenne muscular dystrophy (DMD) is a genetic, progressive neuromuscular disease caused by mutations in the dystrophin protein which compromise the integrity of the sarcolemma." (PMID 41288941, 2025). "Duchenne muscular dystrophy (DMD) is caused by mutations in the DMD gene, resulting in dystrophin deficiency in skeletal/cardiac muscle and progressive loss of function." (PMID 41038271, 2025). "Duchenne muscular dystrophy (DMD) is a severe X-linked hereditary disorder caused by pathogenic variants in the DMD gene encoding the dystrophin protein." (PMID 41614822, 2025). "Duchenne muscular dystrophy (DMD) is a fatal X-linked inherited muscular disorder caused by mutations in the DMD gene." (PMID 40940738, 2025). "Duchenne muscular dystrophy (DMD) is a fatal X‐linked disease caused by mutations in the DMD gene, leading to dystrophin deficiency and progressive degeneration of skeletal and cardiac muscles." (PMID 41030228, 2025). "Duchenne muscular dystrophy (DMD) is caused by pathogenic sequence variants occurring in the DMD gene which lead to the loss of the dystrophin protein, a molecular 'shock absorber' that protects muscle from contraction-induced injury." (PMID 40817386, 2025). "Duchenne muscular dystrophy (DMD) is a X-linked disease caused by mutations in DMD encoding dystrophin." (PMID 40688418, 2025). "Duchenne muscular dystrophy (DMD) is a progressive myopathic condition caused by dystrophin gene mutation and is linked to cardiac fibrosis and arrhythmias." (PMID 40857738, 2025). "Duchenne muscular dystrophy (DMD) is an inherited X-linked disease caused by a loss-of-function mutation in the gene encoding dystrophin; the dystrophin protein plays a key role in skeletal muscle fiber integrity." (PMID 40214585, 2025). "Duchenne Muscular Dystrophy (DMD), which is the most common form of Muscular Dystrophy, is caused by mutations in the dystrophin gene." (PMID 38812789, 2024). "Duchenne muscular dystrophy (DMD) is an X-linked, recessive, degenerative neuromuscular disorder caused by mutations in the DMD gene, which encodes dystrophin protein." (PMID 38640165, 2024). "Duchenne muscular dystrophy (DMD) is a progressive and degenerative myopathy that occurs due to mutations in the DMD gene on the X‐chromosome encoding the cytoskeletal protein dystrophin." (PMID 38658324, 2024). "Duchenne muscular dystrophy (DMD) is a fatal X-linked recessive muscle disease caused by mutations in DMD, which encodes the dystrophin protein." (PMID 38785523, 2024).
Duchenne muscular dystrophy (continued). "Dystrophin (DMD) gene mutations, causing Duchenne muscular dystrophy, lead to compromised sarcolemma integrity and secondary proteostasis imbalance, culminating in dilated cardiomyopathy." (PMID 38329532, 2024). "Duchenne muscular dystrophy (DMD) is another rare diagnosis causing a decrease in the production of the protein dystrophin; it affects 1 in 5000-to-6000 people assigned male at birth, with a prevalence rate estimated to be 10 cases per 100,000 males." (PMID 39062264, 2024). "Clinical trials delivering high doses of adeno-associated viruses (AAVs) expressing truncated dystrophin molecules (microdystrophins) are underway for Duchenne muscular dystrophy (DMD)." (PMID 38713520, 2024). "Cardiac arrhythmias significantly contribute to mortality in Duchenne muscular dystrophy (DMD), a severe muscle illness caused by mutations in the gene encoding for the intracellular protein dystrophin." (PMID 38099845, 2024). "Like previous studies that used DMD-deficient primary myoblasts or CRISPR/Cas9-induced DMD knockouts to model Duchenne muscular dystrophy in 3D-TESMs, the knock down of DMD resulted in a significantly reduced force-generating capacity." (PMID 38389096, 2024). "Duchenne muscular dystrophy (DMD) is a recessive genetic disorder characterized by progressive muscle degeneration caused by truncating mutations in the dystrophin gene (DMD), located on the X chromosome." (PMID 38596212, 2024). "Duchenne muscular dystrophy (DMD) is a fatal muscular degenerative disease with incidence of 1 in 3500–5000 males caused by frameshifting mutations in the gene encoding dystrophin." (PMID 38589794, 2024). "Duchenne muscular dystrophy (DMD) is an X-linked genetic disorder caused by mutations in the dystrophin gene, with an incidence of approximately 1 in 5,000 male births." (PMID 39290213, 2024). "Duchenne muscular dystrophy (DMD) is a serious and progressive genetic disorder caused by mutations in the DMD gene." (PMID 39328620, 2024). "Becker muscular dystrophy (BMD), like the closely related Duchenne muscular dystrophy (DMD), is caused by variants in the dystrophin (DMD) gene, resulting in progressive muscle degeneration and muscle weakness." (PMID 39250335, 2024). "Duchenne muscular dystrophy (DMD) is an intractable X-linked muscular dystrophy caused by mutations in the DMD gene." (PMID 38702481, 2024). "Duchenne muscular dystrophy (DMD) is a devastating, progressive neuromuscular disorder caused by X-linked recessive mutations to the dystrophin gene (DMD) located on chromosome Xp21." (PMID 39056750, 2024). "Duchenne Muscular Dystrophy (DMD) is a fatal muscle disorder caused by mutations in the dystrophin gene (DMD) that results in cycles of muscle fiber degeneration and regeneration." (PMID 38690566, 2024). "Mutations in the dystrophin gene cause Duchenne muscular dystrophy (DMD), Becker muscular dystrophy (BMD), and isolated cardiac disease (manifesting as DCM)." (PMID 38308002, 2024). "Furthermore, mutations in Dystrophin cause Duchenne muscular dystrophy (DMD)." (PMID 39387251, 2024). "Duchenne muscular dystrophy (DMD, OMIM 310200) is an incurable, X-linked recessive form of muscular dystrophy caused by mutations in the dystrophin gene (DMD) located on chromosome Xp21.2." (PMID 38689355, 2024). "Duchenne muscular dystrophy (DMD) is an X-linked genetic muscle-wasting disorder arising from mutations in the dystrophin gene (DMD) resulting in aberrant expression of the dystrophin protein." (PMID 38602028, 2024). "Progressive muscle weakness, chronic inflammation and cardiomyopathy are characteristic features of Duchenne muscular dystrophy (DMD), an X-linked muscle disease resulting from a loss of dystrophin function." (PMID 38770680, 2024). "Duchenne muscular dystrophy (DMD) is a rare X-linked neurodegenerative disorder caused by mutations in the DMD gene." (PMID 39719075, 2024).